CD9 (CD9 molecule)
Diseases named in the same sentence as CD9 in open-access papers (continued):
Sharing a sentence is not in itself a finding about the gene and the disease.
tumor (continued). "Blood samples were obtained 5 weeks after the transplantation of Yamato-SS cells in order to investigate the correlations between tumor growth and MCT1+CD9+ EV levels." (PMID 33920416, 2021). "So far, this notion is supported by recent studies of the role of tetraspanins CD9 and CD81 in metabolism of glutamate and lipids in normal or tumor tissues." (PMID 33919420, 2021). "In fact, this scenario highly resembles the well-established established tumor-suppressive role of tetraspanins CD82, CD9, and TSPAN8 in epithelial-origin cancers, whereby they regulate E-cadherin/β-catenin complex-dependent cell-cell adhesion." (PMID 33919420, 2021). "To further verify that the isolated pellets were exosomes, we analyzed levels of the exosome-specific markers (CD9 and CD63) in tumor cells and pellets isolated from their respective media." (PMID 33618729, 2021). "Some tetraspanins, such as TSPAN15, can enhance tumor cell proliferation ability, while other family members, such as CD9, CD63, TSPAN1, TSPAN7, and TSPAN31, can antagonize apoptosis and facilitate tumor cell survival." (PMID 34540692, 2021). "We observed a significant correlation between tumor volume and MCT1+CD9+ expression levels on EVs (R = 0.860, p = 0.003)." (PMID 33920416, 2021). "Exposure to NCCR resulted in an increase in the tumor exosomal markers (CD63 and CD9) expression in the post-NCCR resected rectum compared to pre-NCCR rectal biopsies." (PMID 34316329, 2021). "At the tissue level, CD9 was found to be predominantly localized at the cell membrane, whereas CD63, CD81, and CD82 were primarily found in the cytoplasm of the tumor samples." (PMID 34065085, 2021). "We detected tumor-derived EVs in supernatants of LLC that were similar to exosomes in terms of size (~109 nm) and protein expression (Hsp70/TSG101/CD9)." (PMID 33510128, 2021). "Recently, EpCAM on tumor-derived EV membrane was also employed as a promising tumor surface marker, while the tetraspanin family of proteins, such as CD63, CD9, and CD81, was mainly used as EV universal markers." (PMID 34900726, 2021). "Only minor differences in overall levels of tetraspanins were observed when comparing normal with disease EVs, whereby CD9 and CD63 appeared to increase, and CD81 decreased, in tumour‐stroma EVs." (PMID 34596356, 2021). "The mean tumor CD63 and CD9 scores respectively in pre-NCCR biopsy was 99 and 130 in patients with low-intermediate NAR score compared to 117 and 144 in patients with high NAR score (P = 0.4934) (P = 0.5519)." (PMID 34316329, 2021). "The results of Western blot analysis also showed that exosomes secreted from 4T1 tumor cells express CD81, CD9, CD63, and TSG101 markers along which β-actin was used as the internal control." (PMID 34194604, 2021). "Further statistical analysis showed that KLF4 expression was positively correlated with the expression of CD9 (r = 0.510, P < 0.01) and CD81 (r = 0.382, P < 0.05) in tumor tissues." (PMID 32350244, 2020). "Tetraspanins CD9 and CD81 frequently serve as the surface markers of exosomes, which are involved in intercellular communication during tumor progression." (PMID 32350244, 2020). "Decreased expressions of CD9 and CD81 were found in most HCC tumor tissues and predicted advanced stages." (PMID 32350244, 2020). "We have also examined the roles of the key co-chaperone CDC37 in the release of EV proteins including CD9 and epithelial-to-mesenchymal transition (EMT), a key event in tumor progression." (PMID 32204513, 2020). "The results showed that both of CD9 and CD81 overexpression significantly inhibited tumor growth, which were in line with the results in vitro." (PMID 32350244, 2020). "Our work demonstrated that both CD9 and CD81 are directly transcriptional targets of KLF4, which has been recognized and addressed as a tumor suppressor in various cancers." (PMID 32350244, 2020).
tumor (continued). "We describe the conditions for detection of MICA in exosomes and prove, for the first time using both techniques, the co-existence in one vesicle of exosomal markers (the tetraspanins CD9, CD63 and CD81) and an endogenously expressed tumour-derived antigen." (PMID 29720199, 2018). "This method is highly specific, allowing the isolation of only small EVs by using general small EV surface markers (e.g., CD81, CD9, and CD63) and even only small EV subpopulations, for example, tumor small EVs by using a tumor-specific marker." (PMID 29951374, 2018). "The top differential edges of this network included at least two tumor suppressor genes (GAS1 and CD9)." (PMID 28506242, 2017). "Human tumor cell (K562, A549, and HCT116)-released exosomes showed vigorous expression of tetraspanins (CD9, CD63, and CD81) with the exception of CD9 on K562 exosomes at approx. 150 nm diameter." (PMID 27101102, 2016). "Patients stratified into subgroups based on different CD9 expression levels in the tumors also segregated known prognostic markers such as age at diagnosis (≤ or > 18 months), and INSS tumor stages 3 or 4 versus stages 1, 2 or 4S." (PMID 27572323, 2016). "In-depth transcriptome analyses and ChIP-qPCR identified the cell surface glycoprotein, CD9, as a major downstream player and direct target of the recently described GRHL1 tumor suppressor." (PMID 27572323, 2016). "For example, we identified several members of the tetraspanins family (Tetraspanin-14, CD9, CD63, and CD81 antigens) to be increased in tumor-derived exosomes from the non-invasive cell line, MCF-7." (PMID 25798887, 2015). "To evaluate the effects of CD9 knockdown on MDA cells in vivo, we compared primary tumor growth and metastasis after implantation of either MDA-Ds-Red or MDA-Ds-Red-CD9sh cells into the mammary fat pad of nu/nu mice." (PMID 25762645, 2015). "All tumor samples showed higher HER1 and CD9 levels in contrast to low-to-moderate expression of membrane-associated MICA and HER2 molecules." (PMID 26579120, 2015). "However, to date, the manner in which CD9 inhibits tumor cell motility remains unclear." (PMID 24520284, 2014). "We have addressed the variation in expression of some common exosomal proteins (CD9, CD81, CD63, Rab5, HSP70, TSTA3) and tumour-specific proteins (i.e. TM9SF4) in plasma exosomes from patients with different solid tumours." (PMID 26082317, 2013). "They showed a uniform population of CD45−, CD56+, CD9+, CD81hi, GD2+ tumor cells with heterogeneous expression of CD57−/+ and CD58+/++; CD90 was positive in all but one tumor, whereas CD271 was partially expressed in only one tumor." (PMID 23472067, 2013). "In the Cox proportional hazards model of LNM, high-ITGA3/CD9, YK4, and the major width of the tumor (size) were reported as independently significant variables." (PMID 24006899, 2013). "We stably expressed tetraspanin CD9 in an invasive and metastatic human fibrosarcoma cell line (CD9-HT1080) to investigate its role in regulating tumor cell invasiveness." (PMID 23840773, 2013). "Five tumor suppressors or suppressor candidates including NRIP3, CYLD, CD9, ATF3 and OXTR were strongly induced by TSA alone." (PMID 18301774, 2008). "In such a model, T-category (P=0.024), N-category (P=0.012) and CD9 expression (P=0.017) retained their significance for DFS, and can consequently be considered as independent factors in predicting tumour failure." (PMID 14735195, 2004). "Notably, these genes contained major BL-specific driver genes, such as CD9, MYC, TP63, and cJUN, indicating a direct tumor cell-intrinsic repression of BL features." (PMID 39762215, 2025). "Alongside HEK293T cells, human primary tumor cell lines MDA-MB-231, MCF-7, and T47D were treated with various dosages of MCP-PhoCl-CD9 and MCP-PhoCl-CD63 VSV-G+ EVs." (PMID 41271724, 2025).
tumor (continued). "To characterize the expression patterns of CD103, CD49a, and CD9 within our patient cohort, we conducted t-distributed Stochastic Neighbor Embedding (t-SNE) analysis, enabling visualization of NK cell distribution across liver and tumor compartments." (PMID 41268557, 2025). "TCGA data analysis and 32 paired ESCC and adjacent non-tumorous tissues microarray revealed that CD9 expression was higher in ESCC tissues than in normal tissues, and was associated with tumor stage or lymph node metastasis." (PMID 40860827, 2025). "THBS2 showed a significant correlation (P < 0.05) with tumor size in CD81 capture for all three groups but not for the CD9 and CD63 capture or the average capture (except the average capture in the all subject group, which has a P value of 0.02)." (PMID 40897818, 2025). "This pattern of reduced functional activity was consistent across various NK cell subsets— including CD103+/CD49a-, CD9+/CD103-/CD49a-, and cNK cells—with the notable exception of tumor-infiltrating ILC1-like cells, which maintained functional capacity similar to that of their liver counterparts." (PMID 41268557, 2025). "CD9 expression showed a strong spatial correlation with FASN expression, indicating these genes may play roles in creating tumor microenvironments that facilitate the transition to invasive cancer." (PMID 40163697, 2025). "Inhibiting these CD9-positive ANXA6-EVs could potentially reduce stromal modification and tumor progression." (PMID 38542378, 2024). "Genetic engineering involves the fusion of tumor-targeting or tumor-penetrating peptides with transmembrane proteins, including LAMP2B, PDGFR, PTGFRN, CD63, CD9, and CD81, on EVs and the expression of the fused protein in donor cells, which produce EVs with the functional peptides on the surface." (PMID 38796692, 2024). "Responders (R, with a decreased tumor size or SD > 6 months) had greater baseline frequencies of CD33hi classical monocytes (CD33hi cMo, p = 0.014) and CD9+ nonclassical monocytes (CD9+ nMo, p = 0.012) than non-responding (NR) patients." (PMID 38493133, 2024). "CD9+MMP9+MMP2-TIMP1- and MMP9+MMP2-TIMP1+ subpopulations of circulating sEVs are the most promising predictors of the efficacy of thermoradiation therapy because their levels at baseline differ significantly in CRCPs with different tumor responses." (PMID 37109070, 2023). "Uptake of CD9-RFP bearing EVs resulted in a more intense signal with respect to that from CD81-RFP fusions, confirming an impaired sorting and partial degradation of the latter in recipient tumor cells." (PMID 36579638, 2023). "Similarly, CD9 is attributed to CSC properties, including tumor formation and the maintenance of tumor cell population." (PMID 36834653, 2023). "We think that the increased release of CD9 and CD81-positive EVs might provide a promising marker to monitor GBM tumor response to radiotherapy." (PMID 36203458, 2022). "In conclusion, Ecad+ EVs and CD45+ EVs, respectively, derived from epithelial cells and immune cells, constituted a minor fraction (11%) of thyroid tissue-derived CD9+/CD81+ EV pool, but showed a doubling in their proportion within the total EV pool of tumor tissue (23%)." (PMID 35453506, 2022). "In summary, CD9 was found to be downregulated or absent in the main tumor mass, but it was still expressed immediately adjacent or within vessels." (PMID 35563166, 2022). "CD9 staining was mainly confined to several small clusters of tumor melanocytic cells that strongly expressed CD9, even in weakly stained sections or with wide negative regions." (PMID 35563166, 2022). "In addition, exosome-specific markers TSG101, CD9, CD63 and CD81 were evaluated in tumor-derived exosomes through different methodologies." (PMID 35804987, 2022). "Additionally, while it appears that the role of CD9 in promoting or inhibiting tumor progression is rather controversial, CD151 and TSPAN8 are believed to be involved in tumor progression, displaying rather oncogenic properties." (PMID 34830819, 2021).
tumor (continued). "Then, IHC, RT-qPCR and western blotting were used to detect CD133, CD9 and Nestin in the absence or presence of HBO in the tumour tissues of mice following intracranial transplantation, and the results showed weak expression of CD133, CD9 and Nestin after HBO treatment." (PMID 33986256, 2021). "From these parental Colo-320 cells we previously generated two stable cell lines, Colo-320/CD9 and Colo-320/ADAM17-KO, which allowed us to study here the specific involvement of CD9 and ADAM17 in the interactions and uptake of tumor exosomes by recipient cells." (PMID 34576100, 2021). "The effective isolation of EVs was confirmed by western blot analysis, with positive signal for the tetraspanins CD9, CD63, CD81 and Tumour Susceptibility Gene 101 (TSG101), while negative for the cellular marker calnexin." (PMID 33216826, 2020). "In this context, Yuh-Ying Yeh and co-workers have identified the tetraspanin, CD9, CD63, and CD37 as abundantly expressed markers in tumor exosomes of CLL patients by flow analysis and immunoblotting, in contrast to the modest expression of CD41, CD56, and CD3." (PMID 32759810, 2020). "As CD9 was not expressed in exosomes throughout all ccRCC cell lines, it cannot serve as a general marker for exosomes from tumor cells." (PMID 33276608, 2020). "Collectively, these observations implied that CD9 and CD81 may function as tumor suppressors in HCC." (PMID 32350244, 2020). "In summary, our findings have identified CD9 and CD81 as potential tumor suppressor genes in HCC, which may mediate KLF4-induced suppression of tumor cell growth via JNK signaling for the first time." (PMID 32350244, 2020). "Taken together, in this study, the acquisition of 5FU and Dox chemoresistance in DP-HCC1806:BMMSCs is likely due to a CAM-DR mechanism, in which CD9, IL6, and CCL5/CCR5 collectively mediate tumor-growth, adhesion and anti-apoptotic signals, via integrin-dependent mechanisms." (PMID 31191817, 2019). "We detected Tspan8, CD9, and CD81 signals on EVs isolated in control and in tumour‐bearing animals." (PMID 30982971, 2019). "The blurred fluorescence of EV-originated Thy-1.1 and CD9 was not visible around tumour-infiltrating GW4869-treated Thy-1.1+ DUC18 CD8+ T cells (right two small photos)." (PMID 29382847, 2018). "Patients with longer time to tumor progression generally exhibited a decrease in circulating CD9+/SVN+ and CD9+/GFAP+/SVN+ exosomes immediately following survivin vaccination; whereas, those with early tumor progression had an increase in exosomes, despite anti-survivin immunotherapy." (PMID 29383115, 2017). "One patient (#7), who was the last of the patients with early progression to progress, experienced a detectable increase in CD9+/GFAP+/SVN+ exosomes 9 weeks following initial vaccination (row 4), which was 16 weeks prior to the detection of tumor progression on brain MRI scanning." (PMID 29383115, 2017). "Compared with CD9-positive cells, CD9-negative or depleted epithelial and tumor cells have a much higher migratory capacity, thereby supporting epithelial restitution." (PMID 29312336, 2017). "Moreover, the fraction of CD9+ exosomes with both GFAP and survivin positivity also showed a significant change at 9 weeks consistent with the patient’s tumor status (p = 0.0225)." (PMID 29383115, 2017). "In the current study, increases in both CD9+/SVN+ and CD9+/GFAP+/SVN+ exosome levels, taken as a fraction of all CD9+ exosomes, proved to be associated with tumor progression; whereas, CD9+/GFAP+ exosomes did not." (PMID 29383115, 2017). "This latter patient (#1) without tumor progression experienced a 98% reduction in serum CD9+/GFAP+/SVN+ exosomes 9 weeks after initial vaccination and a 94% reduction at 22 months." (PMID 29383115, 2017). "In addition to the HER1/2 levels, we analyzed expression levels of surface markers CD9 and MICA on the mono-dispersed patient tumor cells." (PMID 26579120, 2015).
tumor (continued). "Interestingly, tumor infiltrating CD56bright NK cells express high levels of two of these dNK markers: CXCR3 and CD9." (PMID 26079948, 2015). "CD26+CD9− cells showed higher invasion activity than that of CD26+CD9+ cells, suggesting that CD9 may suppress tumor cell invasion." (PMID 24466195, 2014). "Detailed studies analyzing CD9 have previously indicated that CD9 alone does not inhibit tumor cell motility." (PMID 24520284, 2014). "Since CD26 interacts with CD9 in an inverse correlation, it is plausible that combined blocking of both CD26 and CD9 may effectively inhibit tumor cell invasiveness." (PMID 24466195, 2014). "Therefore, we particularly focused on sunitinib resistance and performed immunohistochemical experiments on tumor samples to validate the discriminatory potential of four new candidate biomarkers, LGALS8, RAB17, EpCAM, and CD9." (PMID 23555683, 2013). "Crossing a CD92/2 (KO) murine model with TRAMP mice (a PCa mouse model showing de novo development of spontaneously metastasising PCa) shows that ablation of CD9 had no detectable effect on de novo primary tumour onset, but increased metastasis to the liver." (PMID 24351670, 2013). "Moreover, RMS cases were also CD45−, CD56+lo, CD90+ and CD57−; two expressed CD81+, CD9+ and CD58+ and one was partially positive for CD99 (40% of tumor cells ), a phenotypic pattern which was specific for this tumor subtype." (PMID 23472067, 2013). "The [high-ITGA3/CD9 and YK4]-positive cases consistently exhibited a higher rate of LNM (around 80%) irrespective of the size strata, but the negative cases revealed an increasing rate of LNM with larger tumor size (>30 mm)." (PMID 24006899, 2013). "Surprisingly, secretion in the 100,000 g pellet of CD9 and Mfge8, 2 other markers classically used to characterize mouse dendritic or tumor cell exosomes, was not reduced in shRab27a-expressing cells." (PMID 24009879, 2012). "We studied 55 hLT biopsies (including 17 cases of secondary hLT) for CD9 and CD9P-1 gene expression, using the CD9 index (CD9 mRNA level in tumour core relative to CD9 mRNA in surrounding tissues) and the CD9P-1 index (CD9P-1 mRNA level in tumour core relative to CD9P-1 mRNA in surrounding tissues)." (PMID 21206492, 2011). "For CD9 gene expression, 27.3% of non-metastatic primary lung tumours (pT × N0) expressed CD9 mRNA more at tumour cores than in their surrounding tissues." (PMID 21206492, 2011). "Intraperitoneal injections of GS-168AT2 in NCI-H460-xenografted Nude mice led to drastic inhibition of tumour growth, as well as to the downregulation of CD9, but not of CD81, in the tumour core." (PMID 21206492, 2011). "Tetraspanins are small transmembrane proteins, such as CD9, CD37, CD53, CD63, CD81, CD82, CD151 and tetraspanin 8, that are involved in a multitude of biological processes, including cell-cell adhesion, metastasis suppression and tumour progression." (PMID 21339979, 2010). "The link between reduced CD9 expression and tumour failure was independent of tumour T and N –categories, as found in the multivariate analysis." (PMID 14735195, 2004). "Therefore, we first purified the tumor cell-derived exosomes and verified them using NTA (NanoSight) and electron microscopy, then examined the exosome-expressed proteins (CD9 and TSG101) using WB." (PMID 40756343, 2025). "Likewise, inhibiting the CD9-positive ANXA6-EVs could potentially reduce the stromal modification and PDAC tumor progression." (PMID 38542378, 2024). "Specifically, miR‐31 directly targets the tumour suppressors CCAAT enhancer binding protein α (CEBPA) and dachshund family transcription factor 1 (DACH1), which decreases β‐catenin protein level via increasing Wnt/β‐catenin signalling inhibitors, such as AXIN1, CD9 and CD82." (PMID 38797942, 2024). "However, CD9 deletion in the MMTV/PyMT mouse model impaired tumor growth, but did not affect tumor initiation or metastasis." (PMID 36941633, 2023).